IFNA1 (interferon alpha 1)
Diseases named in the same sentence as IFNA1 in open-access papers (continued):
Sharing a sentence is not in itself a finding about the gene and the disease.
infection (2,813 papers, 1988 to 2026). The state of being infected such as from the introduction of a foreign agent such as serum, vaccine, antigenic substance or organism. "We measured the IFN induction levels in the mouse lungs by extracting total RNA from homogenized lung tissue at 1 day post-infection, and performed qRT-PCR to detect IFNα1, IFNβ, IFNγ, and IFNλ3 expression levels." (PMID 38315735, 2024). "Here we found that Nlrp3−/− mice showed defective expression of Ifna1, and bore significantly higher titer of virus in the lung compared to WT mice 3 days after infection." (PMID 36746963, 2023). "By RT-PCR analysis of cell lysates at 24 hours post-infection (h.p.i.)we observed the robust induction of IFNA1, IFNB and IFNL1." (PMID 36439115, 2022). "During wt RVFV infection, IFNα1 and λ mRNA expression was up-regulated and interestingly, IFNλ showed the highest increase in both trophoblast cell lines." (PMID 34835071, 2021). "Paradoxically, a few groups have shown that systemically administering either recombinant IFNβ or hybrid IFNα1/α8 concurrently with infection alleviated cerebral malaria (P. berghei ANKA)." (PMID 33408718, 2020). "MOPV infection of mDCs induced a 10- (IFNα1) to 80- (IFNα2) fold increase in IFN-I production relative to that of mock-infected cells when cocultured with T cells." (PMID 30419076, 2018). "PR/8 infection induces an early response in type I IFN genes IFNA1 and IFNB as well as type III IFN genes IL-29 and IL-28A, although the degree of increase was slightly less than that of most type I IFN genes." (PMID 22396727, 2012). "IFNα1 mRNA peaked 24h post-infection, while IFNβ was elevated 48h post-infection." (PMID 38315735, 2024). "Here we showed that the replication capacity of the TA strain was higher than the TT variant, peaking at 23-fold higher by 48 h post infection still much lower than what was seen for cell cultures not pretreated with IFNα-1." (PMID 23431359, 2013). "During early infection, IFNB and IFNA1 (human) or Ifna4 (mouse) are exclusively expressed through IRF3, triggering the expression of IRF7, which is required for the transcription of the other IFNA subtypes." (PMID 38543729, 2024). "The RNA levels of many type I IFN genes, including Ifna13, Ifna7, Ifna1/5/6, Ifna1/2/5, Ifna4, Ifnab, Ifna12, and Ifnb1, were significantly increased in IEC4.1 cells 24 h post-infection." (PMID 36928642, 2023). "Infection also results in enhanced expression of several IFN stimulated genes, especially IFNA1, IFNB1, and TLR3 transcripts." (PMID 31474994, 2019). "The synthesis of IFNα1, IFNα2, and IFNβ mRNAs after MOPV infection started as early as eight hours post-infection (hpi), peaked at 24 hpi, and then decreased to reach the level of that of uninfected cells at 40 hpi." (PMID 30419076, 2018). "NY/238 infection markedly stimulated CXCL10 mRNA, NY/238 virus also triggered an early increase in the expression of RIG-I and IFNA1 genes and increased mRNA levels of antiviral gene ISG56 and CCL chemokine CCL5." (PMID 22396727, 2012). "We conclude that IFNA1, IRF3, CXCL8, CXCL10, IFNB1, and CHUK are the key hub genes involved in the H5N1 human infection, which makes a major contribution towards the inflammation or cytokine storm leading to the prognosis of the disease and critical clinical outcomes." (PMID 37515084, 2023). "Similarly, the majority of upregulated genes in HIEs at 24 hours post-infection with VA1 are involved in type I and III IFN signaling, including IFNL1, IFNA1, and IFNB1, and numerous downstream ISGs." (PMID 35935957, 2022). "Furthermore, while IFNAR2 blockade (which repressed the IFNβ-IRF7 forward feedback loop) did not affect the expression pattern in the high MOI infection, it significantly repressed all subtypes except IFNα1, -α2, and -α8 after low MOI infection." (PMID 33542718, 2020).
infection (continued). "At 6 hours post-infection, the levels of IFNβ (IFNB) remained nearly unchanged, while the levels of IFNα1 (IFNA1) and the other antiviral effectors like MxA, ISG 56, OAS and PKR were only marginally increased in cells infected with the wild type BAC36 virus compared to mock infected cells." (PMID 20485504, 2010). "We initially tested the possible role of acetate in IFN-β production and found increased expression of Ifnb1, but not Ifna1, in the lung of RSV-infected mice treated with acetate compared to untreated RSV-infected mice 3 and 5 days after infection." (PMID 31332169, 2019). "Interestingly, C2-202 induced a much higher type I (IFNα1, IFNβ) and type III (IFNλ3), but not type II (IFNγ) response compared with TN/94-49 infection." (PMID 38315735, 2024). "Further infection of cells with UV treated KSHV virions revealed almost undetectable levels of IFNβ transcripts (inclusive of the downstream ISG54) and failed to activate the IFNA1 promoter transcription activity (our present study)." (PMID 20485504, 2010). "Similarly, neuronally-produced Ifna1 may be required for microglial and MC interferon-signaling and anti-viral responses in WNE – potentially more so in MCs, since MCs and not microglia expressed its cognate receptor, Ifnar1 during infection." (PMID 37016414, 2023).
tumor (1,452 papers, 1983 to 2026). "Accelerated tumor growth in MC-deficient mice was accompanied by significant inhibition of Ifna1, which was normalized upon BMMC reconstitution." (PMID 37686555, 2023). "It is well established that type I interferons, IFNB1 and IFNA1, play a crucial role in the anti‐tumor immune response." (PMID 38627900, 2024). "Re-stimulation of lymphocytes ex vivo with gB498-505 peptide demonstrated an increase in the number of endogenous gB-specific CD8+ T cells in the spleen, tumor and lymph nodes of mice vaccinated with IFNα1 or IFNβ compared to vaccination alone." (PMID 34552594, 2021). "In this case, IFNA1 presumably acts directly on the tumor cell and on its environment and thereby unfolds its therapeutic effect." (PMID 33240813, 2020). "The recombinant IFNA1 mimics a viral infection and leads to an antiviral program in the patient and its tumor tissue." (PMID 33240813, 2020). "IFNA1 is approved under defined conditions for the treatment of a variety of tumor types including mCRC alone or in combinations." (PMID 33240813, 2020). "TAMs from SNAIL1 depleted tumors displayed increased expression of M1-like/anti-tumor genes like Ifna1, Il12a, Il6, Nos2, and Ifnb1." (PMID 29593211, 2018). "Patients who underwent PD blockade therapy with higher IFNA1 expression within tumor tissues positively correlated with better prognosis, which is consistent with this study." (PMID 30389912, 2018). "Lastly, we provide evidence for possible down-stream effects of adrenoceptor-mediated suppression of pDC function showing suppression of IFNA1-dependent increased tumor cell lysis by epinephrine." (PMID 23724117, 2013). "Suppression of TLR9-mediated IFNA1 secretion from PBMCs by adrenoceptor stimulation reduced the lytic activity of NK cells on K562 tumor cells." (PMID 23724117, 2013). "The influence of modified IFNA1 secretion on NK cell activity was evaluated using a colorimetric tumor cell lysis assay." (PMID 23724117, 2013). "Another gene increased greatly in transformed IEC-6 cells was Ifna1, which played an important role in angiogenesis of tumor." (PMID 19397828, 2009). "Therefore, whilst both IFNα1- and IFNβ-vaccination has the capacity to increase tumor-specific T cell infiltration into the TME, only IFNβ resulted in a therapeutic benefit." (PMID 34552594, 2021). "Furthermore, IFNβ-vaccinated mice showed significantly higher numbers of tumor-specific CD8+ T cells in the spleen and tumor relative to IFNα1-vaccinated mice suggesting successful tumor-infiltration of functional, tumor-reactive CD8+ T cells." (PMID 34552594, 2021). "DEG analyses revealed the genes contributing to RFS and related to SUVmax (PSG5, TFF3, SOX2, SLC5A5, and SLC5A7) and tumor size (HOXD10, IFNA1, and FER1L6)." (PMID 38745021, 2024). "Four genes (IFNA1, IFNG, LEP, and PLG) were excluded from analysis because their PCR Ct values were greater than 32 for both tumor and control samples, indicating that the expression of these genes was extremely low and not reliable for comparison analysis." (PMID 35600354, 2022). "We also identified three DEGs (HOXD10, IFNA1, and FER1L6) related to tumor size." (PMID 38745021, 2024). "In addition, expression level of IFNA1 and IFNB1 increased with tumor grade in case of ER-positive BC, whereas it decreased in case of ER-negative BC." (PMID 35593921, 2022). "In the fifteen sensitive tumor cell lines, a weak constitutive expression of IFNA1 in the absence of the virus was found in six tumor cell lines (Meso35, 36, 37, 56, 34 and 122) and was increased in the presence of MV in four of these (Meso35, 36, 34 and 122)." (PMID 26539644, 2015). "On the contrary, tumor cell lines that are unable to develop a type I IFN response are sensitive to MV infection, with the four exceptions, Meso36, 37, 34 and 122, which express IFNA1, IFNB1 and MX1 and are sensitive to MV replication." (PMID 26539644, 2015).
tumor (continued). "Constitutive expression of IFNA1 was observed in the absence of MV in all healthy cells and in all insensitive tumor cell lines, with the exception of Meso173." (PMID 26539644, 2015). "In the nine other sensitive tumor cell lines, we never detected IFNA1 expression, either in the presence or absence of MV." (PMID 26539644, 2015).
cancer (802 papers, 1984 to 2026). A tumor composed of atypical neoplastic, often pleomorphic cells that invade other tissues. "And the finding demonstrated a strong correlation between elevated levels of immune checkpoints and the SREBF1 in ACC, notably KIR2DL3, IL2RA, CD80, IFNG, BTN3A2, and IL1A, also IFNA1 wass significantly associated with SREBF1 in the majority of cancers." (PMID 40668814, 2025). "Ifna1 plays a pivotal role not only in antiviral immunity but also in the surveillance of cancer development." (PMID 19397828, 2009). "IFNA1 has an antitumor effect that inhibits proliferation; thus, low expression of IFNA1 could lead to cancer cell proliferation." (PMID 38745021, 2024). "Moreover, IFNA1 expression level positively correlates with better survival in human cancer patients." (PMID 30389912, 2018). "In contrast, a few individual genes, such as BAX, CLAR, HMGB1, HSP90A11, IFNA1, and PDIA3, showed weak correlations with the ICD scores in most cancer types." (PMID 38627900, 2024). "We found that IFNA1 and IFNL1 gene transcripts resulted negligibly expressed across the pan-cancer dataset when compared to other immunosuppressive and pro-inflammatory cytokines such as TGFB1/2, PTGES2, IL1A, IL1B, IL6 and CSF1." (PMID 38239354, 2023). "IFNα (1 × 104 IU/mL) was capable of direct cancer cell cytotoxicity in 4/8 (50%) of wtGISTc tested, while no significant cancer cell cytotoxicity was mediated by IFNγ (1 × 103 IU/mL)." (PMID 36142281, 2022). "In addition, three interferons (IFNA1, IFNA2, and IFNE) and MIR31HG (microRNA-31 Host Gene) were also in the top 10 for these two cancers." (PMID 32033319, 2020). "Cancer cells undergoing ICD require cell surface calreticulin (CRT) exposure, induction of EIF2α-dependent reticulum stress, high mobility group box 1 (HMGB1) and ATP release, and the expression of type 1 IFNs (Ifnα1 and Ifnβ1) and chemokines (Cxcl 9 and Cxcl 10)." (PMID 36090972, 2022). "Unlike HMGB1, IFNA1, IFNA2, IL-2, KIR2DL3, IL-13 and NCAPG2 demonstrated an intuitive correlation in only a few cancer types." (PMID 36776838, 2023).
bacterial infections (94 papers, 2009 to 2026). "The main result was that IFNα1 and IFNγ, at their optimal doses, induced expression of CD169 on monocytes and of CD64 on neutrophils, respectively, at levels similar to what happens physiologically during the course of natural viral or bacterial infections." (PMID 32031762, 2020).
brain disease (4 papers, 2014 to 2025). "GIFN mice specifically express Ifna1 in the brain and universally develop severe brain disease in early life, including intracerebral calcification, confirmed by micro-computed tomography (CT) and alizarin red staining, which is also a characteristic neuroradiological feature of AGS." (PMID 38878770, 2024).
IFNA1 also shares sentences with these, for which no sentence is quoted: melanoma (288 papers); autoimmune disease (275); hepatoma (135); ZIKV infection (131); hepatitis C (125); depression (117); chronic hepatitis B (106); asthma (97); psoriasis (84); rheumatoid arthritis (67); multiple sclerosis (65); Cirrhosis (63); co-infection (60); hepatitis B (51); dengue (50); Hepatitis (50); diabetes (49); Aicardi-Goutières syndrome (48); lung carcinoma (48); viral diseases (48); leukemia (47); Sjögren’s syndrome (47); dermatomyositis (45); Sepsis (43); renal cell carcinoma (42); chronic myeloid leukemia (41); infectious disease (41); Obesity (41); liver fibrosis (39); viral hepatitis (39).
A further 692 diseases each share a sentence with IFNA1 in 38 papers or fewer.